ATP1A1 (ATPase Na+/K+ transporting subunit alpha 1)
Diseases named in the same sentence as ATP1A1 in open-access papers (continued):
Sharing a sentence is not in itself a finding about the gene and the disease.
renal carcinoma (4 papers, 2017 to 2025). A carcinoma arising from the epithelium of the renal parenchyma or the renal pelvis. "CCK-8 assays demonstrated that ATP1A1 knockdown significantly enhanced the proliferative capacity of renal carcinoma cells." (PMID 40821775, 2025). "In vitro functional assays confirmed that ATP1A1 knockdown significantly enhanced the proliferative, migratory, and invasive capabilities of renal carcinoma cells (A498 and 786-O), suggesting a suppressive role for ATP1A1 in malignant tumor progression." (PMID 40821775, 2025). "Our in vitro and in vivo data of ATP1A1 inhibitory roles in RCC progression suggest that ATP1A1 is a potential novel suppressor protein for renal cancer." (PMID 28484360, 2017). "Our work indicates ATP1A1 is a novel potential suppressor protein for renal cancer based on ATP1A1 inhibition roles for RCC progression in vitro and in vivo." (PMID 28484360, 2017). "Many studies have shown that SLC12A1, ATP1A1, and PDHA1 are low-expressed in renal cancer and play an important role in the development of tumors." (PMID 32699530, 2020). "In this study, we analyzed the databases of GEO, TCGA, GEPIA, Oncomine, and found that six genes (SUCLG1, PCK2, GLDC, SLC12A1, ATP1A1, and PDHA1), are related to the survival prognosis of patients with renal cancer." (PMID 32699530, 2020). "It has been reported that Solute carrier family 12 member 1 (SLC12A1), Sodium/potassium-transporting ATPase subunit alpha-1 (ATP1A1) and Pyruvate dehydrogenase E1 component subunit alpha (PDHA1) are differentially expressed in renal cancer tissues." (PMID 32699530, 2020).
adrenal adenomas (3 papers, 2018 to 2025). "Microarray analysis was performed using five APAs with ATP1A1 mutations and five non–functioning adrenocortical adenomas (NFAs)." (PMID 34681640, 2021). "Transcriptome and immunohistochemical analysis showed that Na/K-ATPase (NKA) expressions in ATP1A1 mutated APA were more abundant than those in non-functioning adrenocortical adenoma or KCNJ5 mutated APAs." (PMID 34681640, 2021). "Indeed, a proportion of patients with primary aldosteronism are now known to harbor adrenal cortical adenomas with heterogeneous molecular alterations (KCNJ5, ATP1A1, ATP2B3, and CACNA1D) involving the calcium/calmodulin kinase signaling pathway." (PMID 29594118, 2018).
Alzheimer disease (3 papers, 2018 to 2024). A progressive, neurodegenerative disease characterized by loss of function and death of nerve cells in several areas of the brain leading to loss of cognitive function such as memory and language. "On the contrary of ATP1a3, ATP1a1 expression did not seem to be affected in Alzheimer’s disease patients." (PMID 38796484, 2024). "In Alzheimer's disease (AD), there is reduced expression of Atp1a3 but not Atp1a1 in the frontal cortex of AD patients as well as impaired NKA activity." (PMID 30623173, 2018).
Ewing sarcoma (3 papers, 2018 to 2024). A small round cell tumor that lacks morphologic, immunohistochemical, and electron microscopic evidence of neuroectodermal differentiation. "To explore the potential of ATP1A1, BCL11B, GLG1, and CD99 as prognostic biomarkers, we analyzed the association of their expression levels with outcome in a large cohort of Ewing sarcoma patients (n = 166)." (PMID 29416716, 2018). "In the current study, comparative expression analyses revealed that ATP1A1, BCL11B, and GLG1 constitute potential specific markers for Ewing sarcoma." (PMID 29416716, 2018). "Collectively, we show that ATP1A1, BCL11B, and GLG1 are EWSR1-FLI1 targets, of which BCL11B and GLG1 offer a fast, simple, and cost-efficient way to diagnose Ewing sarcoma by immunohistochemistry." (PMID 29416716, 2018). "While CD99 showed broad expression in many different tumor entities, ATP1A1, BCL11B, and GLG1 were only expressed at low levels in every tumor entity relative to Ewing sarcoma, indicating a higher specificity for this disease than CD99." (PMID 29416716, 2018). "Further analyses indicated that while ATP1A1 exhibited high specificity (90%), it had no additional value for establishing Ewing sarcoma diagnosis if it was combined with BCL11B and GLG1." (PMID 29416716, 2018). "In addition to these findings in vitro, gene-set enrichment analyses of either ATP1A1-, BCL11B-, or GLG1-correlated genes within 166 primary Ewing sarcoma tumors revealed that the most significantly (min." (PMID 29416716, 2018).
gastric cancer (3 papers, 2024 to 2025). A primary or metastatic malignant neoplasm involving the stomach. "Clinically, ATP1A1 expression correlates with tumor T stage and venous invasion in gastric cancer and holds prognostic significance in ovarian cancer." (PMID 40821775, 2025). "In gastric cancer, ATP1A1 expression shows a correlation with histological type, pathological T stage, and intravascular invasion, and high expression of ATP1A1 significantly reduces the overall survival rate of patients." (PMID 38730618, 2024). "The ATPase Na+/K+ transporting subunit alpha 1 (ATP1A1), a key NKA component, regulates ionic balance and cell volume, and contributes to gastric cancer progression by modulating interferon (IFN) and MAPK signaling." (PMID 41459506, 2025).
heart failure (3 papers, 2018 to 2025). Inability of the heart to pump blood at an adequate rate to meet tissue metabolic requirements. "Among these DEGs, ATP1A1 was involved in the Superpathway of Inositol Phosphate Compounds and also contributed to both heart failure and arrhythmia." (PMID 32423033, 2020). "Consistently, our IPA pathway analysis showed that ATP1A1 was involved in heart failure." (PMID 32423033, 2020).
liver cancer (3 papers, 2015 to 2021). An epithelial or non-epithelial malignant neoplasm that arises from the liver. "Second, the underlying mechanisms of impacts of ATP1A1 knockdown on liver cancer cells need further explorations." (PMID 26334094, 2015).
primary aldosteronism (3 papers, 2016 to 2025). An endocrine disorder characterized by excessive production of aldosterone by the adrenal glands. "Several studies have confirmed the tumorigenic role of this mutation as it was mutually exclusive to ion channel-related (KCNJ5, ATP1A1, ATP2B3, and CACNA1D) mutations in primary aldosteronism." (PMID 29594118, 2018).
secondary hypertension (3 papers, 2013 to 2025). High blood pressure caused by an underlying medical condition. "Studies have shown that sodium/potassium-transporting ATPase subunit alpha-1 is an enzyme encoded by the ATP1A1 gene, and mutations in this gene have been associated with APAs and secondary hypertension." (PMID 24376526, 2013).
triple-negative breast carcinoma (3 papers, 2024 to 2025). An invasive breast carcinoma which is negative for expression of estrogen receptor (ER), progesterone receptor (PR), and human epidermal growth factor receptor 2 (HER2). "Although it is essential for ionic homeostasis, ATP1A1 is hypomethylated and overexpressed in aggressive tumors such as triple-negative breast cancer (TNBC)." (PMID 40723891, 2025).
age-related hearing loss (2 papers, 2022 to 2023). "We saw no age-related changes in Atp1a1 expression in the SV/SL, although reduced expression of the Na,K-ATPase (correlated to reduced endocochlear potential) has been documented in a gerbil model of age-related hearing loss." (PMID 35454087, 2022).
aldosterone-secreting adenomas (2 papers, 2016 to 2022). "A gain of function such as development of a leak current is possible but has not yet been demonstrated for ATP1A3, although somatic mutations in ATP1A1 found in aldosterone-secreting adenomas induced significant leak currents." (PMID 26990090, 2016). "Aldosteronomas are a major cause of unilateral PA, associated with somatic variants in KCNJ5, CACNA1D, ATP1A1, ATP2B3, CLCN2, CACNA1H and CTNNB1 genes." (PMID 35813615, 2022).
Arrhythmia (2 papers, 2020 to 2026). Any cardiac rhythm other than the normal sinus rhythm. "SCN5A knock-down reduced contraction amplitude (-51.9% ± 37.2, p < 0.01) without inducing arrhythmias, whereas combined GJA5 and ATP1A1 knock-down induced significant irregularity (403% ± 371.3, p < 0.001), increased conduction heterogeneity (+18%), and reduced velocity (-52.4%)." (PMID 41868610, 2026).
cutaneous melanoma (2 papers, 2020 to 2024). A primary melanoma arising from atypical melanocytes in the skin. "Investigating 448 cutaneous melanomas from the TCGA PanCancer Atlas, we discovered a positive correlation between high ATP1A1 mRNA expression and markers of differentiation and pigmentation (MITF, SOX10, TYR, MLANA)." (PMID 38178183, 2024). "ATP1A1 expression was significantly higher in cholangiocarcinoma, skin cutaneous melanoma and thymoma (THYM) (all p < 0.001) than in the adjacent normal tissues." (PMID 32684846, 2020).
esophageal cancer (2 papers, 2016 to 2026). A primary or metastatic malignant neoplasm involving the esophagus. "In conclusion, our findings suggest that ATP1A1 expression might potentially be helpful in the diagnosis and staging of esophageal cancer." (PMID 27845894, 2016).
Insulin resistance (2 papers, 2024 to 2025). Increased resistance towards insulin, that is, diminished effectiveness of insulin in reducing blood glucose levels. "Functional enrichment analysis revealed that upregulated genes were involved in PI3K binding (e.g. PIK3IP1, IRS2, ATP1A1), insulin resistance and FOXO signalling genes while downregulated genes were overrepresented by metabolic and immune processes." (PMID 39593143, 2024).
metastatic melanoma (2 papers, 2016 to 2024). A melanoma that has spread from its primary site to another anatomic site. "The primary objective of this study was to determine the role of ATP1A1 in the prognosis of metastatic melanoma and its association with the resistance to targeted therapy." (PMID 38178183, 2024). "To conclude, our study highlights the potential of ATP1A1 as a valuable prognostic marker for metastatic melanoma patients, as well as a predictive marker for the response to targeted therapy." (PMID 38178183, 2024). "The combination of digitoxin and MEK inhibitor thus synergistically extended the survival of mice with metastatic melanoma in a manner that depended on human ATP1A1." (PMID 27545456, 2016).
osteosarcoma (2 papers, 2025). A usually aggressive malignant bone-forming mesenchymal neoplasm, predominantly affecting adolescents and young adults. "Further analysis of paired human osteosarcoma tissues confirmed the upregulation of ATP1A1 mRNA, with its high expression strongly associated with poor prognosis." (PMID 40665639, 2025). "Collectively, these findings suggest that the cytoplasmic interaction between LncDARS‐AS1 and ATP1A1 plays a pivotal role in regulating the oncogenic behavior of osteosarcoma cells." (PMID 40665639, 2025). "This study establishes that LncDARS‐AS1 promotes osteosarcoma progression by regulating ATP1A1 expression and modulating Na+/K+‐ATPase (NKA) activity." (PMID 40665639, 2025). "Previous experiments demonstrated a direct interaction between LncDARS‐AS1 and ATP1A1, with both functioning as oncogenic drivers in osteosarcoma by promoting tumor proliferation and metastasis." (PMID 40665639, 2025). "Functional assays demonstrated that knockdown of ATP1A1 significantly suppressed osteosarcoma cell proliferation and metastasis." (PMID 40665639, 2025). "Further analysis of the TARGET‐OS dataset showed that ATP1A1 expression was significantly higher in patients who succumbed to osteosarcoma compared to those who survived." (PMID 40665639, 2025). "In conclusion, this study provides novel insights into the molecular interactions between LncDARS‐AS1 and ATP1A1 in osteosarcoma progression." (PMID 40665639, 2025). "In summary, LncDARS‐AS1 modulates NKA activity by stabilizing ATP1A1, thereby maintaining ionic equilibrium in osteosarcoma cells." (PMID 40665639, 2025). "In this study, five possible key targets of SS against osteosarcoma were finally identified: ATP1A1, CLK1, SIGMAR1, PYGM, and HSP90B1." (PMID 40831924, 2025). "This study identifies LncDARS‐AS1 as a novel oncogenic regulator that stabilizes ATP1A1 and enhances Na+/K+ ATPase activity, promoting osteosarcoma metastasis." (PMID 40665639, 2025). "This study delineates the critical roles of the oncogenic long non‐coding RNA LncDARS‐AS1 and the Na+/K+‐ATPase subunit ATP1A1 in driving pulmonary metastasis in osteosarcoma." (PMID 40665639, 2025). "Immunohistochemical analysis of 169 tumor samples further supported the link between high ATP1A1 expression and adverse prognosis in osteosarcoma patients." (PMID 40665639, 2025). "Initial findings established that both LncDARS‐AS1 and ATP1A1 are markedly overexpressed in osteosarcoma and act as oncogenic drivers by promoting tumor cell proliferation and metastasis." (PMID 40665639, 2025). "The analysis revealed a significant upregulation of ATP1A1 in osteosarcoma tissues." (PMID 40665639, 2025). "Therefore, this study aims to explore the molecular mechanism by which LncDARS‐AS1 promotes osteosarcoma metastasis through the regulation of ATP1A1." (PMID 40665639, 2025). "Analysis of high‐throughput sequencing data from osteosarcoma patients in the GEO and TARGET‐OS datasets revealed significantly elevated ATP1A1 expression in tumor tissues, particularly among patients with poor clinical outcomes." (PMID 40665639, 2025). "Collectively, the results provide novel insights into the post‐transcriptional regulation of ATP1A1 by LncDARS‐AS1 and identify both molecules as promising candidates for therapeutic intervention and prognostic stratification in osteosarcoma." (PMID 40665639, 2025). "Despite these limitations, the study reveals a previously unrecognized post‐transcriptional regulatory mechanism by which LncDARS‐AS1 stabilizes ATP1A1 and enhances Na+/K+‐ATPase (NKA) activity, ultimately promoting osteosarcoma progression." (PMID 40665639, 2025). "RT‐PCR validation of paired osteosarcoma tissue samples from 94 patients confirmed the upregulation of ATP1A1 in osteosarcoma tissues, with a positive correlation between the RNA expression levels of LncDARS‐AS1 and ATP1A1 in the same cohort." (PMID 40665639, 2025).
osteosarcoma (continued). "Based on network pharmacology and transcriptomics, we identified ATP1A1, CLK1, SIGMAR1, PYGM, and HSP90B1 as the key targets of solasonine that influence the progression of osteosarcoma cells." (PMID 40831924, 2025). "Subcellular localization analysis in 143B and U2OS/MTX300 osteosarcoma cells, based on qPCR and Western blotting, showed that both LncDARS‐AS1 and ATP1A1 were predominantly localized in the cytoplasm, suggesting that their interaction primarily occurs within this compartment." (PMID 40665639, 2025). "Subsequently, stable ATP1A1 knockdown 143B and U2OS/MTX300 cell lines were successfully established, along with stable ATP1A1 overexpression in HOS and U2OS osteosarcoma cell lines." (PMID 40665639, 2025). "Targeting the LncDARS‐AS1/ATP1A1/NKA axis, including pharmacological inhibition with digoxin, offers promising opportunities for the development of new therapeutic strategies against osteosarcoma." (PMID 40665639, 2025). "It is speculated that ATP1A1, CLK1, SIGMAR1, PYGM, and HSP90B1 may serve as therapeutic targets for solasonine in the treatment of osteosarcoma." (PMID 40831924, 2025).
renal fibrosis (2 papers, 2022 to 2023). A final common manifestation of a wide variety of chronic kidney diseases characterized by glomerulosclerosis and tubulointerstitial fibrosis. "Obviously, 4-PBA cotreatment indeed inhibited the activation of ER stress and also prevented BV-induced E- to N-cadherin switch and the proteins involved in pro-EMT or renal fibrosis, while restoring the expressions of AQP1, ATP1A1, and SLC22A6 in human renal tubule epithelia." (PMID 35873571, 2022).
adrenocortical carcinoma (1 paper, 2021). "ATP1A1 L104R mutation were modulated in human adrenocortical carcinoma (HAC15) cells (ATP1A1-mutant cells), and we evaluated cell proliferation and molecular signaling events." (PMID 34681640, 2021).
Alpha-thalassemia (1 paper, 2022). Alpha-thalassemia is an inherited hemoglobinopathy characterized by impaired synthesis of alpha-globin chains leading to a variable clinical picture depending on the number of affected alleles. "These genes included laminin subunit beta 1(LAMB1), ATPase Na+/K+ transporting subunit alpha 1 (ATP1A1), alpha thalassemia/mental retardation syndrome X-linked (ATRX), and methyl-CpG binding domain protein 1 (MBD1)." (PMID 36389237, 2022).
arenavirus infection (1 paper, 2018). "Using a modified LCMV, we identified two host-cell proteins called ATPase Na+/K+ transporting subunit alpha 1 (ATP1A1) and prohibitin (PHB) as factors that promote arenavirus infection." (PMID 29462184, 2018).
Barrett esophagus (1 paper, 2016). Esophageal lesion lined with columnar metaplastic epithelium which is flat or villiform. "Because we only measured serum ATP1A1 expression in ESCC patients, whether the presence of ATP1A1 upregulation in patients with Barrett's esophagus is unknown." (PMID 27845894, 2016).
Batten disease (1 paper, 2018). "Other authors not only proved the interaction between proteins CLN3 and Na/K ATPase ATP1A1, but also showed that functions of ATP1A1 as a pump were not significantly affected in patients with Batten disease." (PMID 30621751, 2018). "Why do the authors not consider the ATP1A1 inhibitors as potential remedies for the treatment of juvenile Batten disease?" (PMID 30621751, 2018).
breast tumors (1 paper, 2022). "Among them, we found that ATP1A1, ATP1A2, ATP1B1, and ATP1B3 are highly expressed in normal breast tissue and among them, ATP1A1 and ATP1B1 are upregulated in breast tumors while ATP1A2 is downregulated and ATP1B3 is unchanged." (PMID 36232400, 2022). "Interestingly, ATP1A1 and ATP1B1 isoforms were overexpressed in breast tumors while ATP1A2 was downregulated in breast tumors and ATP1B3 mRNA expression was unchanged." (PMID 36232400, 2022). "In turn, present results suggest that the treatment of patients with OU or possibly other CGs could be pursued only after the molecular characterization of breast tumors has evidenced a high expression of ATP1A3 and a low expression of ATP1A1 and ATP1B1." (PMID 36232400, 2022).
cardiac hypertrophy (1 paper, 2009). "This included two traditional markers of cardiac hypertrophy (MHC-β and Atp1a1/SERCA)." (PMID 20003209, 2009).
cervical carcinoma (1 paper, 2022). A carcinoma arising from either the exocervical squamous epithelium or the endocervical glandular epithelium. "Additionally, a previous study has demonstrated that downregulation of the expression of sodium pump α1 (ATP1A1) and α3 (ATP1A3) subunits is linked to arenobufagin-triggered cytotoxicity in cervical carcinoma Hela cells." (PMID 36235115, 2022).
Cirrhosis (1 paper, 2021). A chronic disorder of the liver in which liver tissue becomes scarred and is partially replaced by regenerative nodules and fibrotic tissue resulting in loss of liver function. "For the moderate cirrhosis group, some targets showeda statistically significant reduction from the control, by 40 to 50%,such as MGST1, MDR1, MRP3, OCT3, and ATP1A1." (PMID 34428046, 2021).
congestive heart failure (1 paper, 2018). Failure of the heart to pump a sufficient amount of blood to meet the needs of the body tissues, resulting in tissue congestion and edema. "The cardiac glycoside ouabain is an inhibitor of ATP1A1 that has been used to treat congestive heart failure in European countries." (PMID 29462184, 2018).
COVID-19 (1 paper, 2021). A disease caused by infection with severe acute respiratory syndrome coronavirus 2. "Our results are in agreement with such studies and indicate that the expression of the two major subunits of the ATP1 gene, namely the ATP1A1 and the ATP1B1, are downregulated in the PBMCs of our COVID-19 patients with low FT3 serum values, as compared to those with normal FT3 serum values." (PMID 34861865, 2021).